IL6 (interleukin 6)
Diseases named in the same sentence as IL6 in open-access papers (continued):
Sharing a sentence is not in itself a finding about the gene and the disease.
COVID-19 (continued). "Many of the already-known disease hallmarks of COVID-19 have been shown to be associated with circulating serum concentrations of specific miRNAs, for instance miR-424, in the likelihood of a thromboembolic event, and miR-766-3p in its association with IL-6-related hyperinflammation." (PMID 34564316, 2021). "Indeed, exposure to UV light (and such induced mediators) may reduce circulating pro-inflammatory cytokines linked to COVID-19 cytokine storm events, including interleukin-6 (IL-6) and c-reactive protein." (PMID 33426009, 2020). "Of note, chronic increase of serum IL-6 levels has been associated with higher risk of cardiovascular events, thus supporting its role in the development of cardiovascular complications (including inflammation-dependent diffuse microangiopathy with thrombosis) in COVID-19 patients." (PMID 33489899, 2020). "Therefore, inhibition of cytokines, and IL-6 specifically, may help prevent severe lung tissue damage caused by cytokine release in COVID-19 patients." (PMID 32764275, 2020). "Since SAA is correlated with IL-6 and involved in the pathogenesis of the risk conditions for severe COVID-19 (obesity, diabetes and atherogenesis), it might also play a role in the pathogenesis of COVID-19 and therefore present a potential biomarker and therapeutic target." (PMID 33679725, 2020). "High levels of IL-6 have been associated with the development of severe disease and acute respiratory distress syndrome during COVID-19 infection, but the role of inflammation markers in COVID-19-induced-AKI remains speculative." (PMID 32880774, 2020). "In addition, abnormal expression of IL-6 has been associated with the pathogenesis of a variety of human diseases, including asthma, cancers and autoimmune diseases such as rheumatoid arthrosis, and recently with COVID-19." (PMID 33066442, 2020). "IL-6 is especially needed when B cells are activated by antigen and differentiate into IgM, IgG and IgA antibodies, which may be associated with the seroconversion during COVID-19 pathogenesis." (PMID 33195318, 2020). "We further found that elevated and a trend of a continued increase in cytokine levels, including IL-2R, IL-6, IL-8, IL-10 and TNFα, and decreased lymphocyte subsets, especially helper T cells, suppressor T cells and NK cells, were associated with a poor prognosis of COVID-19." (PMID 33365277, 2020). "Hence, the frequent symptoms found in this sample suggest that headache related to COVID-19 may be linked to meningeal irritation, in line with the previously commented IL-6 pathophysiological mechanisms related to calcitonin gene-related peptide release." (PMID 33391152, 2020). "Therefore, tocilizumab can effectively treat severe patients of COVID-19, which might be explained by the blocking of IL-6–associated febrile and inflammatory storm response." (PMID 32350134, 2020). "COVID-19 severity and outcomes are closely related to the characteristics of the immuneresponse and subsequent cytokine storm incited by pathogenic T cells and inflammatory monocytes with a high level of IL-6 secretion, which are more severe in elderly patients." (PMID 33269102, 2020). "Importantly, elevated IL-6 (>70 pg/ml) levels as well as other cytokines (after multivariate adjustment for sex, age, ethnicity, comorbidities) were associated with reduced survival (HR 2.47, p < 0.0001) of patients hospitalized for COVID-19 in New York (USA)." (PMID 33426009, 2020). "Furthermore, recent COVID-19 studies indicate that high levels of IL-6 may be associated with COVID-19 infection, and that the inhibition of IL-6 may be beneficial in extenuating the disease." (PMID 32485858, 2020). "Moreover, elevated IL-6 levels are associated with COVID-19 severity and mortality." (PMID 32766256, 2020).
COVID-19 (continued). "In addition, an elevated IL-6 level (OR for each 10 pg/mL increase, 1.646; 95% CI, 1.167–2.322; P = 0.005) was noticed to be independently associated with the progression to critically ill cases among septic COVID-19 patients." (PMID 33178716, 2020). "This case underscores the potential importance of early serial measurements of IL-6 and cytokine storm-associated acute phase reactants, such as ferritin, D-dimer, and C-reactive protein, in guiding clinical decision-making in the management of patients with suspected COVID-19." (PMID 32635353, 2020). "Furthermore, since the rs180079 SNP of the interleukin 6 (IL6) gene has been affected by the severity of several types of lung diseases, including chronic obstructive pulmonary disease (COPD) and pneumonia, the IL6 polymorphism is presumed to confer susceptibility to COVID-19." (PMID 33396837, 2020). "So far overlooked is the fact that both IL6 and hypoxia depress the abundance of a key anticoagulant, Protein S. We speculate that the IL6-driven cytokine explosion plus hypoxemia causes a severe drop in Protein S level that exacerbates the thrombotic risk in COVID-19 patients." (PMID 32826388, 2020). "Severe COVID-19 cases showed elevated IL-6, TNF-α, and IFN-γ, while asymptomatic individuals had broader, milder cytokine profiles." (PMID 41993206, 2026). "This analysis shows that several inflammatory and viral cytokines remain elevated beyond the acute phase and are associated with cognitive deficits, including IL-6, IL-13, IL-8, IL-1β, TNFα, and MCP1 in long-term post-COVID-19 patients." (PMID 41516418, 2026). "The interleukin-6 (IL-6) inhibitors tocilizumab and sarilumab have been repurposed for COVID-19 treatment." (PMID 42140959, 2026). "At Day 1, COVID-19 exhibited significantly higher IL-6, IL-10, and CXCL10; FluA showed an attenuated cytokine response." (PMID 41683886, 2026). "This suggests that 7a contributes to the elevated levels of proinflammatory cytokines, such as IL-6 and IL-12, observed in sera obtained from severe COVID-19 patients." (PMID 41400356, 2026). "Several studies have reported the maintenance of elevated IL-6 in COVID-19 patients and in those with neurological symptoms." (PMID 41516418, 2026). "The review encompasses interleukin-based therapeutic strategies, where several IL-1 and IL-6 inhibitors were studied across clinical trials, but only tocilizumab has shown some promise against severe COVID-19." (PMID 41683812, 2026). "AAG seems to represent inflammatory pathways as levels correlate with IL-6 and CRP, specifically NETosis and IL-6 expression, potentially as part of the cytokine storm seen in severe COVID-19." (PMID 41557029, 2026). "Concordant with our study, A1AGP glycoprotein levels were shown elevated in severe COVID-19 and in vitro studies, reduced NETosis and upregulated IL-6." (PMID 41557029, 2026). "Background/Objectives: Severe COVID-19 is marked by IL-6-driven inflammation, endothelial injury, and dysregulated coagulation." (PMID 41595788, 2026). "sCD14ST showed a very good correlation with IL-6, confirming its value as a biomarker of the COVID-19-induced inflammatory response." (PMID 39941649, 2025). "In conclusion, it is reported that COVID-19 patients hospitalized in the ICU had higher mean levels of IL-6 and zinc compared to the other virus-infected groups and the control group." (PMID 40756075, 2025). "Critically ill COVID-19 patients frequently exhibit a cytokine storm, characterized by elevated levels of cytokines such as IL-6, IL-8, IL-12, TNFα, IL-17, MCP-1, IP-10, and IL-10." (PMID 40160814, 2025). "Individually, serum IL-6 was identified early in the COVID-19 pandemic and has been reported to be increased in severe vs non-severe COVID-19, an independent predictor of ICU admission, and higher in COVID-19 deaths than survivors." (PMID 40424310, 2025).
COVID-19 (continued). "A cross-sectional study reported that patients with both periodontal disease and COVID-19 exhibited salivary levels of IL-6 and experienced a greater number of respiratory symptoms compared to individuals with COVID-19 alone." (PMID 41462931, 2025). "Hyperglycemia is associated with increased cytokine storm - IL-6 and CRP levels - and immune dysfunction - decreased lymphocytes, and T cells - in COVID-19." (PMID 40314776, 2025). "Cytokine levels are a crucial factor in the renal pathology of COVID-19 patients, compared to other viral infections, resulting in elevated levels of cytokines such as IL-1β, IL-6, IL-18, and TNF-α." (PMID 40863220, 2025). "IL-6, although investigated less frequently, had elevated values in all investigated patients in the COVID-19 subgroup (100%), compared to 50% in the COVID-19 + EBV subgroup." (PMID 40427060, 2025). "Recent studies have established that immune dysregulation in severe COVID-19 cases is driven by the excessive production of IL-6 and TNF-α, leading to a hyperinflammatory state known as the cytokine storm." (PMID 40137715, 2025). "Among circulating mediators, IL-6 has emerged as one of the most reproducible biomarkers of COVID-19 severity." (PMID 41517263, 2025). "Higher levels of most soluble mediators were observed in the COVID-19 group than in the healthy control group, with major increases in the levels of proinflammatory cytokines, including IL-6, TNF-α and IFN-γ." (PMID 40608806, 2025). "Several studies have also shown a gradual decrease in IL-6 concentrations over time in patients recovering from COVID-19, suggesting its involvement in the resolution of systemic inflammation and its potential utility as a longitudinal biomarker of recovery." (PMID 41226453, 2025). "In cases of severe or critical COVID-19, the use of dexamethasone, interleukin-2 or interleukin-6 inhibitors, or Janus kinase inhibitors is recommended, alongside optimal supportive and intensive care." (PMID 41155576, 2025). "IL-6 is a pro-inflammatory cytokine often elevated in severe COVID-19 and frailty syndromes in older adults." (PMID 41020118, 2025). "Elevated IL-6 levels have been consistently linked to renal function and susceptibility to ESRD and to AKI in COVID-19 patients." (PMID 40430148, 2025). "High levels of IL-6 exacerbate the clinical course of severe COVID-19, as these patients often develop interstitial pneumonia, multi-organ damage, and immune-mediated pulmonary thrombosis." (PMID 40647649, 2025). "In conclusion, our study contributes to the growing evidence highlighting the elevation of inflammatory cytokines with their derived ratio (IL-6/IL-10) and miR-155 expression in COVID-19 patients." (PMID 41203712, 2025). "IL-6 as a predictive marker for COVID-19 is well established, it is also reportedly predictive of mortality in patients with cardiovascular disease or end stage kidney disease." (PMID 39210228, 2025). "In COVID-19, elevated levels of IL-6 contribute to the hyperinflammatory state observed in cytokine storms." (PMID 40410684, 2025). "Clinically, high plasma IL-6 levels correlate with platelet hyperreactivity in diseases marked by chronic inflammation, including COVID-19, autoimmune disorders, and certain malignancies." (PMID 40497942, 2025). "The selected indicators (viral load, IL-6 concentration, epithelial damage) were identified as key determinants of COVID-19 severity, which is supported by numerous studies demonstrating their strong correlation with disease progression." (PMID 40431602, 2025). "The presence of higher IL-6 levels in patients with post-COVID-19 condition is also supported by a meta-analysis specifically focused on this biomarker." (PMID 41516235, 2025). "A critical element in COVID-19 severity is IL-6, a cytokine crucial in managing inflammatory responses." (PMID 40571942, 2025).
COVID-19 (continued). "In patients with severe COVID-19, the activation of systemic inflammatory response can promote QTc prolongation by increasing IL-6, resulting in cardiac electrical remodeling." (PMID 40438117, 2025). "As expected for the underlying condition, the COVID-19 positive group exhibited elevated inflammatory markers, including CRP, ESR, IL-6, and ferritin, alongside reduced absolute lymphocyte counts." (PMID 40733560, 2025). "Cytokine storms mediated by interleukins (ILs) (IL-6 and IL-8), resulting from the over-activation of innate immune responses, play a crucial role in the pathogenesis of COVID-19 and other systemic inflammatory syndromes." (PMID 40728559, 2025). "Studies indicate that in severe cases of COVID-19, IL-6 levels can be nearly three times higher than in milder cases." (PMID 39781525, 2025). "To ensure the robustness of our approach, we validated the method with established positive control outcomes where IL6 signaling inhibition has proven efficacious, including for rheumatoid arthritis, polymyalgia rheumatica, and COVID-19." (PMID 39633572, 2025). "The upregulation of the expression of IL-6 and its receptor in COVID-19 can lead to increased activation of endothelial cells, resulting in the excessive release of TF." (PMID 40821797, 2025). "Recent studies have also highlighted strong associations between SNPs of IL6 (rs2069840) and IL10 (rs1800872) genes and the severity of COVID-19." (PMID 40881695, 2025). "Severe COVID-19 is frequently characterized by a hyperinflammatory state, often termed a “cytokine storm,” which entails elevated levels of interleukin-6 (IL-6), C-reactive protein (CRP), and other pro-inflammatory cytokines." (PMID 39857695, 2025). "A major observation in this meta-analysis is the significant relationship between elevated interleukin levels, mainly IL-6 and IL-10, and adverse COVID-19 outcomes." (PMID 41585373, 2025). "In COVID-19 patients, elevated levels of IL-6 are crucial in the occurrence of cytokine storm, QT syndrome, and Torsades de Pointes." (PMID 40438117, 2025). "The verified model simulates the dynamics of moderate, severe, and critical COVID-19 progressions using measured data on lung epithelium damage, viral load, and IL-6 levels as key indicators of disease severity." (PMID 40431602, 2025). "Its receptor antagonists tocilizumab and sarilumab have shown potential benefit in selected patients with severe COVID-19, particularly in hyperinflammatory subgroups characterized by markedly elevated C-reactive protein and IL-6 concentrations." (PMID 41567206, 2025). "Assessing the levels of IL-6 in the circulatory system can serve as a reliable indicator for predicting the likelihood of mortality in COVID-19 patients." (PMID 40438117, 2025). "More evidence links COVID-19 to cytokine release syndrome, specifically elevated pro-inflammatory cytokines (IL-1β, IL-6, TNF-α, and IL-1α) in extreme cases." (PMID 41293155, 2025). "COVID-19 is characterized by a systemic inflammatory response with elevated cytokines, including IL-6, IL-1β, TNF-α, and interferon-γ." (PMID 41446486, 2025). "Patients with COVID-19 exhibit cytokine storm and abnormally high levels of inflammatory mediators, including IL-6, tumor necrosis factor-alpha (TNF-a), and C-reactive protein (CRP)." (PMID 41002604, 2025). "Among the 19 intersecting targets identified between G. pentaphyllum compounds and COVID-19-associated genes, several key nodes—IL1B, IL6, TNF, ACE, and REN—emerged as central in both the protein–protein interaction and compound–target networks." (PMID 41471341, 2025). "Our study suggests that individuals with both COVID-19 and T2D displayed increased IL-6 levels relative to individuals with COVID-19 only." (PMID 40471558, 2025).
COVID-19 (continued). "In non-SOT control patients, higher expression of proinflammatory cytokines such as IL-6 correlated with COVID-19 severity, consistent with prior studies." (PMID 39794319, 2025). "IL-6 is a key cytokine in the COVID-19 cytokine storm and serves as an independent predictor of lung injury severity." (PMID 40872762, 2025). "The investigation of IL-6 inhibitors, such as tocilizumab, as treatment options for COVID-19 patients has been driven by the clinical consequences of elevated IL-6 levels." (PMID 40647649, 2025). "Comorbidities related to blood and blood-forming organs were generally in positive correlation with the clinical outcome and IL-6 of COVID-19 patients." (PMID 40868247, 2025). "This process is regulated by IL-6 in an inflammatory context, as described for mTreg from severe COVID-19 patients." (PMID 39934117, 2025). "Patients who experienced severe and serious COVID-19 demonstrate an increase in IL-6 at the peak of their symptoms." (PMID 40497938, 2025). "The levels of inflammatory biomarkers such as CRP (p < 0.0001), PCT (p < 0.0001), D-dimer (p = 0.0214), and IL-6 (p < 0.0001) were significantly higher in patients who died of COVID-19 compared to the recovered patients." (PMID 40241896, 2025). "IL-6, IL-10, IL-6/IL-10 ratio, and miR-155 expression were evaluated by ROC curve analyses for prediction ability for COVID-19 severity and mortality." (PMID 41203712, 2025). "By activating SARS-CoV-2 and other toll-like receptors, a variety of proinflammatory mediators, including IL-6 and IL-1β, are released, potentially contributing to the pathology of COVID-19." (PMID 41002604, 2025). "While IL-6 production increases FGF23 and FGF23 functions to reduce vitamin D, it is unclear if low vitamin D levels in COVID-19 are associated with an inability to downregulate IL-6 and prevent a cytokine storm." (PMID 40687705, 2025). "Serum IL-6 levels were significantly elevated in patients diagnosed with COVID-19 compared to healthy controls." (PMID 40621180, 2025). "Compared to females, IL-6 (Mann–Whitney U = 2653, p = 0.0241) and CRP (Mann–Whitney U = 7350, p = 0.0055) were increased in omicron-variant COVID-19 male patients, while IL-6 also increased in the delta variant (Mann–Whitney U = 3200, p = 0.0254)." (PMID 40868247, 2025). "Research shows that in patients with COVID-19, IL-8 concentrations reliably indicate disease severity and provide more accurate clinical predictions compared to IL-6." (PMID 40497938, 2025). "A link has been identified between high levels of the pro-inflammatory cytokine IL-6 in serum and adverse outcomes for COVID-19 patients." (PMID 40471558, 2025). "The cytokine storm seen in severe COVID-19—involving elevated levels of interleukins (IL-6, IL-1β) and tumor necrosis factor-α (TNF-α)—increases thrombin generation and fibrin deposition." (PMID 41458994, 2025). "This review specifically explored the interleukin class cytokines IL-1, IL-6, IL-17, and IL-23 and considered the potential of biologics targeting these cytokines to alleviate severe outcomes in both COVID-19 and aging individuals." (PMID 40333142, 2025). "Although the current thought is that IL-6 is more predictive of COVID-19 outcomes and the severity of disease progression, this finding calls for further research, especially in human subjects, to better elucidate the implication of IL-1 levels." (PMID 40333142, 2025). "Compared to the control group, COVID-19 patients showed significantly higher levels of IL-6, IL-10, IL6/IL-10 ratio, and miR-155 relative expression (p-values < 0.001)." (PMID 41203712, 2025). "In COVID-19, the systemic inflammatory response can escalate into a cytokine storm, including IL-1, IL-2, IL-6, TNF-α, IFN-γ, IP-10, GM-CSF, MCP-1, and IL-10—some of which correlate strongly with disease severity." (PMID 40806851, 2025). "Compared with their parents, who were positive for COVID-19, IL-6, IL-4, and IL-12 were modulated (downregulated) by TEN." (PMID 39941142, 2025).